TNC (tenascin C)
Diseases named in the same sentence as TNC in open-access papers (continued):
Sharing a sentence is not in itself a finding about the gene and the disease.
tumor (continued). "In addition to tumor stromal cells, tumor cells also secrete numerous ECM components, primarily collagens, fibronectin, laminins, hyaluronan, tenascin C, and periostin, which are highly expressed in metastatic tumors and contribute to building tumor metastasis niches." (PMID 35033172, 2022). "TNC is generally absent or suppressed in most normal adult tissues, while it is markedly overexpressed in some pathological conditions, such as wound healing, inflammation, and in a variety of neoplasms." (PMID 36672527, 2022). "The cell binding study was repeated using these primary tumor cell lines and showed a binding profile very similar to 786-O, with strong binding to fibronectin, collagen VI, and collagen XII and inefficient binding to or repulsion by periostin, lumican, and tenascin C." (PMID 34884982, 2021). "Tenascin-C (TNC), an extracellular matrix molecule protein, activates Wnt/β-catenin signaling via downregulation of DKK1, a Wnt pathway inhibitor, thereby promoting pNET cell survival, angiogenic switch, tumor progression, and lung micrometastasis in RIP-Tag2 mice." (PMID 34680266, 2021). "For some experiments, it is relevant to use a TNCKO host to mimic the TNC‐negative condition as host TNC plays a role in promoting lung metastasis by impacting tumor cell survival and plasticity in the blood vessel invasions (BVI), an important precursor of metastasis." (PMID 33988305, 2021). "Moreover, a dual ECM targeting strategy using an anti-tenascin-C aptamer and cationic CPP demonstrated that cationic CPP might facilitate NP movement in tumor tissue." (PMID 32241176, 2020). "A CCK8 assay to assess A673 and SKNMC cell viability showed that the proliferation rates of the TNC-ko groups were significantly lower than those of the TNC-wt groups (p < 0.01) and that the addition of exogenous TNC failed to rescue tumour cell growth in both the TNC-wt and TNC-ko groups." (PMID 31649319, 2019). "Although not specifically shown in cancer, tenascin C therefore could indirectly support tumor survival in the blood by promoting platelet recruitment and activation." (PMID 26539408, 2015). "This evidence supports the hypothesis that TNC plays a multifaceted role in LC progression, participating in processes such as cell migration and invasion, metastasis, angiogenesis, EMT, immune evasion, drug resistance, as well as tumor progression and poor prognosis." (PMID 40981103, 2025). "Additionally, co-culture system of PDAC cells and PSCs have shown an enhanced interaction between cancer cells and axonal DRG through secretion of extracellular matrix glycoprotein tenascin C by PSCs, which may be positively related to PNI, tumor stage and tumor recurrence." (PMID 37834436, 2023). "Interestingly, IL-33 could transform non-stem cells to GBM stem cells, activate disintegrin and metalloproteinase with thrombospondin motifs 5 (ADAMTS5) and EGFR by promoting the accumulation of tenascin-C (TNC), which in turn exacerbates GBM tumor cell proliferation." (PMID 35572545, 2022). "Now we wondered whether TNC influenced the localization of macrophages and other immune subtypes which we addressed by tissue staining in the 11‐week model (Fig EV2) and observed that CD45+ leukocytes were present inside the stroma as well as in the tumor cell nests." (PMID 33988305, 2021). "However, we also emphasize the fact that no ECM protein exists in isolation and suggest that, even targeting such potent molecule as TNC alone, may not be sufficient to completely damage the neoplasm and benefit patient outcome." (PMID 32817625, 2020). "In the current study, we demonstrate that the EWS-FLI1 oncoprotein, which is characteristic of ES, enhances TNC expression by directly binding to its promoter region and that integrin α5β1-mediated YAP activation may be responsible for MALAT1 upregulation in TNC-induced ES tumour progression." (PMID 31649319, 2019).
tumor (continued). "However, as the multivariate Cox regression analysis in the present study failed to reveal Tenascin-C as an independent prognostic parameter for overall survival (p=0.354), the role as a potential prognostic tumor marker for NSCLC patients remains inconclusive." (PMID 26967391, 2016). "Additionally, the fact that CD44 and Tenascin C are expressed at much higher levels in the perivascular astrocytes when compared to peritumoral astrocytes suggests subtle differences between the two populations of non-neoplastic tumor astrocytes." (PMID 22393407, 2012). "As tenascin C has antiadhesive properties, we tested previously in a tenascin C knockout mouse model, whether it is the driver for fibronectin fiber relaxation in tumor tissues, however, the fibronectin fibers lost their tension in tumor tissues even in the absence of tenascin C31." (PMID 39917413, 2025). "No positive correlations were observed for ACTA2, COL11A1, TNC, and PDPN genes in PanCK(-) AOIs at EOCC tumor center or at LOCC tumor invasive margin." (PMID 37964075, 2023). "By comparing the bulk tumor with the peritumoral area, we found a significant up-regulation of all the three ECM proteins, POSTN, TnC, and OPN, in the TRS in both the MetS and non-MetS iCCA." (PMID 36902188, 2023). "In a mouse model, TNBC tumor-bearing mice exhibit an enhanced expression of extracellular matrix proteins, such as fibronectin, tenascin-C, and periostin, in the lungs compared to non-TNBC tumor-bearing mice." (PMID 36835116, 2023). "Tenascin C is a tumor-specific extracellular matrix glycoprotein mainly secreted by CAFs, which is highly expressed in most solid tumors TME, but not in normal adult tissues, and promotes tumor progression." (PMID 36762192, 2023). "In addition, upregulation of tenascin-C and p-EGFR was observed in the recurrent tumors and inhibiting p-EGFR signaling significantly delayed recurrence without affecting initial tumor regression." (PMID 26581390, 2015). "However, tenascin-C derived from each cellular source had a dramatically different impact on the TAM phenotype; only tumor-derived tenascin-C could induce a pro-tumor TAM phenotype, as opposed to CAF-derived tenascin-C." (PMID 33718177, 2021).
cancer (317 papers, 2001 to 2026). A tumor composed of atypical neoplastic, often pleomorphic cells that invade other tissues. "TNC is an ECM glycoprotein and abnormally high expression of TNC has been associated with numerous diseases, including several cancers." (PMID 39915455, 2025). "The increased expression of tenascin-C has been linked to the development of a number of illnesses, such as inflammatory conditions, cancer, and cardiovascular diseases." (PMID 40699873, 2025). "Pathological disorders, including cancer metastasis, autoimmune illnesses, tissue fibrosis, and chronic inflammation, have all been linked to the dysregulated expression or function of tenascin-C." (PMID 40699873, 2025). "The causes of TNC overexpression include cancer, cardiovascular diseases, and other chronic disorders." (PMID 40564778, 2025). "Several other extracellular stroma-associated proteins specifically linked to CTSK, including SPARC and TNC, are reportedly highly expressed in cancer tissue and promote the invasion and metastasis of multiple cancers." (PMID 38594611, 2024). "TNC had missense mutations in either the initial clone or a disseminated clone of triple-proficient and chemonaive cancers, but only the clonal mutation was predicted to be damaging (TNCP1790L, PolyPhen-2 score, 0.99; TNCR1637C, PolyPhen-2 score, 0.38)." (PMID 38175731, 2024). "Tenascin C (TNC) expression has been associated with multiple cancer processes, including enhanced proliferation, migration, and immunosuppression." (PMID 38731867, 2024). "Tenascin-C is highly expressed by cancer-associated fibroblasts and stromal cells, as well as by some cancer cells, and has been involved in promoting proliferation, migration, angiogenesis and metastasis." (PMID 35008401, 2022). "TNC is not only associated with epithelial–mesenchymal transition, proliferation, and migration of cancer cells, but it also facilitates the formation of cancer stroma, including desmoplasia and angiogenesis." (PMID 34320931, 2021). "In cancer, tenascin-C is highly expressed in cancer-associated fibroblasts (CAF) and endothelial cells, as well as in some cancer cells, and has been implicated in promoting survival, proliferation, migration, angiogenesis, and metastasis." (PMID 34564696, 2021). "Another cancer-associated ECM protein is tenascin C (TNC), a matricellular hexameric glycoprotein that binds to ECM proteins, such as fibronectin, and their cell membrane receptors, thereby altering the affinity between the two." (PMID 34638240, 2021). "TnC is upregulated in many human pathologies, and although it has been most extensively studied in the context of cancer, its immunomodulatory role also associates it with inflammatory diseases." (PMID 33996833, 2021). "When neovascular sprouting is induced, loss of TSP-1 and secretion of new ECM proteins (POSTN, TNC, TGFβ1) trigger reawakening of cancer cells." (PMID 31963820, 2020). "This relationship between periostin and tenascin-c is linked to their association with lung metastasis and promotion of cancer cell migration, proliferation and invasion." (PMID 31936750, 2020). "Up-regulation of tenascin-C correlates with situations of tissue repair, and increased tenascin-C protein levels have been detected in human cancers and are associated with a poor prognosis, higher aggressiveness, and malignancy." (PMID 32340328, 2020). "For this purpose, we performed IHC using antibodies against smooth muscle actin (SMA), transforming factor (TGF)-beta and tenascin C, which serve as markers for cancer-associated fibroblasts, cytokines and the extracellular matrix, respectively." (PMID 31138877, 2019). "GBM highly expresses the cancer-associated tenascin-C variants containing the type III-A2 domain, which have the functional site of TNIIIA2." (PMID 31261783, 2019). "TNC is highly expressed during inflammation and several malignant cancers and its expression levels are associated with a poor prognosis in cancer patients." (PMID 31195598, 2019).
cancer (continued). "TNC expression is frequently observed in human cancer and increasing evidences show its association with key clinical parameters, such as relapse-free or overall survival." (PMID 31798767, 2019). "Among them, tenascin-C variants containing the alternatively spliced domain type III-A2 are highly expressed in malignant tumors." (PMID 31261783, 2019). "Conversely, low expression of tenascin-C and fibronectin in cancer tissues is typical in low-risk patients, namely in the early stages of the disease." (PMID 30925774, 2019). "The present study showed that TNIIIA2, which is derived from the cancer-associated variants of tenascin-C, stimulated GBM cell proliferation in an autocrine/paracrine manner through the induction of PDGF expression." (PMID 31261783, 2019). "Tenascin-C expression by fibroblasts has been associated with disease in a number of cancers including bladder, brain and colon but only definitively linked with poor prognosis or survival in breast and lung." (PMID 29416729, 2018). "Here, we report that Twist1, a key regulator of cancer-associated fibroblasts, directly upregulates Prrx1, which, in turn, increases the expression of Tenascin-C (TNC)." (PMID 30069061, 2018). "It is interesting to note here that by altering macrophages we also observe profound differences in markers of cancer-associated fibroblasts (CAFs), with a striking downregulation of αSMA, tenascin C, collagen, and tissue stiffness." (PMID 29719257, 2018). "We recently reported that GCs regulate myofibroblasts, decreasing production and secretion of a number of factors linked to cancer progression and invasion: tenascin C (TNC), TGFβ, HGF/SF." (PMID 27717848, 2017). "In carcinomas, tenascin-C expression in the bulk was associated with T-stage (p=0.006), presence of lymph node (p=0.004) and distant organ metastases (p=0.007)." (PMID 28978001, 2017). "In the present study, we found that HIF1α expression in cancer cells was positively associated with the expression of Tenascin-C in cancer cells, and this finding suggests that hypoxia promotes Tenascin-C expression in ESCC cells." (PMID 26731558, 2016). "Tenascin-C expression in cancer cells was associated with TAM population (p = 0.043), cancer recurrence (p = 0.014), and HIF1α expression in cancer cells (p = 0.004)." (PMID 26731558, 2016). "TNC on the other hand, plays a major role in promoting cell migration by remodeling cancer-associated stroma and activating integrin pathway and has thus been associated with local and distant recurrence." (PMID 27487140, 2016). "The clinical relevance of Tenascin-C expression and the correlation between Tenascin-C expression and expression of other factors related to cancer-associated fibroblasts (CAFs) were also determined." (PMID 26731558, 2016). "Persistent tissue expression of tenascin-C is a pathological hallmark of cancer and chronic inflammation." (PMID 27256716, 2016). "In this study, the survival analysis showed that Tenascin-C expression in stromal fibroblasts and cancer cells was associated with poor OS and DFS." (PMID 26731558, 2016). "Since its discovery, Tenascin-C has been reported to be strongly associated with tumorigenesis and cancer progression in many different types of tumors." (PMID 26731558, 2016). "In particular, the large tenascin-C variants have been linked with reduced focal adhesion activity and enhanced cell migration and matrix degradation, processes that favour cancer progression." (PMID 27256716, 2016). "The increased expression of TPM1, TPM2 and TNC indicates a fundamental reprogramming of normal lung fibroblasts such that they exhibited a gene expression pattern that is typically found in carcinoma-associated fibroblasts." (PMID 25924783, 2015). "From the beginning of its discovery, tenascin-C has been strongly associated with tumorigenesis and cancer progression in many different types of tumors." (PMID 24495796, 2014).
cancer (continued). "TNC was an extracellular matrix glycoprotein which was frequently up-regulated in a variety of cancers and has been implicated in the modulation of cell migration, proliferation, invasion and angiogenesis." (PMID 22920603, 2012). "For instance, TNC was shown to stimulate cancer cell proliferation by inducing EDNRA, the gene encoding the receptor for endothelin-1, and by preventing cells from adhering to fibronectin." (PMID 22481923, 2012). "Our results are in concordance with the data found in the literature, where TNC has been described to be associated with poor OS in a meta-analysis studying TNC expression in multiple types of cancers [N = 2,732, 18 studies, pooled HR of 1.73 (1.29–2.32), p < 0.001]." (PMID 41450913, 2025). "The higher expression of DUSP4 and TNC in co-cultured turtles indicated a lower risk of cancer." (PMID 38540060, 2024). "PRRX1 has been also implicated in a positive feed-back loop in which TWIST1 directly increased PRRX1 which subsequently induced Tenascin-C that itself stimulated TWIST1 activity in Cancer associated fibroblast (CAF), and in dermal and fetal Human lung fibroblast lines." (PMID 37261432, 2023). "TNC, a major component of the cancer-specific matrix, has been found overexpressed in solid tumors, and its expression is associated with poor prognosis in several cancers, including PDAC." (PMID 35681634, 2022). "Here, we review what is known about expression of all four tenascin family members in tumors, followed by a more thorough discussion on tenascin-C and tenascin-W focusing on their oncogenic functions and their potential as diagnostic and/or targetable molecules for anti-cancer treatment purposes." (PMID 35785162, 2022). "The overexpression of periostin and TNC is induced by skin damage, promoting the activation of fibroblasts to repair the wound, and their pathogenicity has been associated with chronic inflammation, fibrosis and cancer." (PMID 32947957, 2020). "TNC, Apo A-IV and 1-MA have been implicated in aggressive forms of cancers." (PMID 31910880, 2020). "Furthermore, the Pathway analysis based on KEGG method indicated that, among the 10 differentially expressed mRNAs, ITGB3, TGFβ2 and TNC were linked to the pathway of MicroRNAs in Cancer." (PMID 33100909, 2020). "However, strict validation of the used antibodies was performed and the inverse association with tenascin-C expression and survival with solid biological background in cancer metabolism reduces the possibility of chance findings." (PMID 28978001, 2017). "The mechanisms for the association of abundant tenascin-C with adverse cancer prognosis may lie in its various mechanisms affecting both the structure of extracellular matrix and functions of cancer cells." (PMID 28978001, 2017). "Tenascin C (TNC) is an extracellular matrix protein that is abundant during early development, is expressed at low levels in adult tissues and is frequently up-regulated in cancer tissues and associated with metastasis and poor patient outcomes." (PMID 28654419, 2017). "In an analysis of endobronchial epithelial-lining fluid of NSCLC patients, Tenascin-C was significantly elevated and the authors suggested that it might be a potential diagnostic tool for early cancer detection." (PMID 26967391, 2016). "Downregulation of tenascin-C by miR-335 or shRNA in human cancer cells in a mouse xenograft model inhibits metastasis formation, and in tenascin-C-deficient mice, metastasis formation of tenascin-C positive cancer cells is also suppressed." (PMID 24495796, 2014). "Therefore, tenascin-C has been implicated as an important target for the treatment of cancer." (PMID 25072631, 2014). "Tenascin-C (TNC) is an extracellular matrix glycoprotein that is widely expressed in the cancer stroma and influences critical processes, such as cell adhesion, migration, and immune modulation." (PMID 40046232, 2025).